CP (ceruloplasmin)
Diseases named in the same sentence as CP in open-access papers (continued):
Sharing a sentence is not in itself a finding about the gene and the disease.
cardiac hypertrophy (2 papers, 2016 to 2017). "As well, compared to diabetic model group, the decrease in both the pathological changes on cardiac hypertrophy and wet heart/body weight ratio in CP extract-treated diabetic mice also indicates cardioprotective potential of CP extract." (PMID 28831132, 2017).
cardiac ischemia (2 papers, 2021 to 2022). "We further observed that urinary KIM-1 levels were increased by myocardial ischemia and reperfusion injury in the presence and absence of VA-ECMO but were unchanged compared to baseline values with Impella CP activation." (PMID 33782857, 2022).
Cholestatic liver disease (2 papers, 2017 to 2021). "Our study findings support the therapeutic potential of CP-MSCs in cholestatic liver diseases and help in understanding the fundamental mechanisms by which CP-MSCs affect energy metabolism." (PMID 29250120, 2017).
chronic osteomyelitis (2 papers, 2018 to 2024). "In order to ascertain the role of CP expression loss in the osteomyelitis rat model, groups of rats were infected with S. aureus strain Reynolds CP5 and its isogenic CP8 and NT derivatives." (PMID 29456969, 2018). "Whereas the loss of CP8 expression by S. aureus HU-85c was due to agrC mutation, the loss of CP is still a trait associated with chronic osteomyelitis." (PMID 29456969, 2018).
cleft palate (2 papers, 2013 to 2023). Cleft palate is a fissure type embryopathy that affects the soft and hard palate to varying degrees. "In mouse and rat models, Gad1 played a role in the normal development of the palate, while a study on the role of miRNAs in the regulation of CP genes found that variants in GAD1 significantly contributed to the human cleft palate phenotype." (PMID 36830605, 2023). "We identified potential causative CP genes in a TGFβ3 knockout model, which may lead to a better understanding of the genetic mechanisms of palatogenesis and provide novel potential targets for gene therapy approaches to treat cleft palate." (PMID 23421592, 2013).
dry eye (2 papers, 2021 to 2025). "This indicates that CP, SF@CP, and SF@CP@Gel possess antioxidant effects that can alleviate oxidative damage to the cornea caused by dry eye, with SF@CP@Gel showing the most significant effect." (PMID 39985258, 2025). "The therapeutic efficacy of the experimental dry eye mouse model was evaluated by determining the clinical indicators, such as tear secretion and corneal fluorescein staining (CFS), after treatment in the CP group and the SF@CP and SF@CP@Gel groups." (PMID 39985258, 2025). "The IL‐10 level in the SF@CP@Gel treatment group was 5.01 times greater than that in the dry eye model without drug treatment group (p < 0.001), and there were significant differences between the SF@CP treatment group and the SF@CP@Gel treatment group (p < 0.05)." (PMID 39985258, 2025).
endometrial cancer (2 papers, 2024 to 2025). Primary or metastatic malignant neoplasm involving the endometrium (mucous membrane that lines the endometrial cavity). "LINC02936 recruits SIX1 to the promoter region of the CP gene, upregulating CP expression and inhibiting ferroptosis in endometrial cancer." (PMID 40191204, 2025).
Ewing sarcoma (2 papers, 2015). A small round cell tumor that lacks morphologic, immunohistochemical, and electron microscopic evidence of neuroectodermal differentiation. "Combining the ERK inhibitor UO126 with CP reduces the proliferation of Ewing’s sarcoma (ES) cells more than UO126 or CP alone." (PMID 25699021, 2015).
fibromyalgia (2 papers, 2018 to 2022). A chronic disorder of unknown etiology characterized by pain, stiffness, and tenderness in the muscles of neck, shoulders, back, hips, arms, and legs. "The level of serum copper and ceruloplasmin (a copper-carrying protein) was elevated in fibromyalgia patients (n = 45) when compared to healthy controls (p < 0.001 and p < 0.001, respectively)." (PMID 36246401, 2022). "Elevated levels of ceruloplasmin have been found in fibromyalgia patients compared to controls, suggesting altered regulation of copper metabolism may be involved in the pathophysiology of FMS." (PMID 30555396, 2018). "Thus, copper and ceruloplasmin may play a role in contributing to the oxidative stress pathogenesis of fibromyalgia." (PMID 36246401, 2022).
flu (2 papers, 2022 to 2024). "Regarding antiinfection prophylaxis measures, both subgroups were comparable, 13 (26%) anti-MPO antibody-positive patients were vaccinated against flu and/or S. pneumoniae (4 in the low ceruloplasmin group and 9 in the high ceruloplasmin group)." (PMID 39388433, 2024).
focal segmental glomerulosclerosis (2 papers, 2021 to 2022). A renal disorder characterized by sclerotic lesions in the glomeruli. "However, uEVs ceruloplasmin was not uniquely linked to DN as it emerged as a potential early biomarker of membranous nephropathy (MN), IgA nephropathy (IgAN), lupus nephritis (LN), and focal segmental glomerulosclerosis (FSGS)." (PMID 36712680, 2022).
food allergy (2 papers, 2016 to 2024). Gastrointestinal disturbances, skin eruptions, or shock due to allergic reactions to allergens in food. "TNF alpha together with faecal calprotectin, alpha 1 antitrypsin beta defensin, EDN, and CP have been proposed as biomarkers of non-IgE-mediated food allergy." (PMID 39085570, 2024).
Fulminant hepatitis (2 papers, 2013 to 2019). Acute hepatitis complicated by acute liver failure with hepatic encephalopathy occurring less than 8 weeks after the onset of jaundice. "The siATP7B-SHED-Hep-transplantation did not improve the increased serum levels of ALT, AST, or total bilirubin, the reduced serum levels of ceruloplasmin and the enhanced expression of copper-induced fulminant hepatitis-associated genes in the fulminant LEC rats 4 weeks of the transplantation." (PMID 30733544, 2019).
fungal infections (2 papers, 2022 to 2024). "The patients with positive bacterial, viral, MP, CP, and fungal infections accounted for 30.04%, 25.92%, 32.55%, 5.74%, and 7.95%, of the total cases, respectively." (PMID 38357505, 2024).
gastric cancer (2 papers, 2023 to 2025). A primary or metastatic malignant neoplasm involving the stomach. "In addition, in patients with stage III–IV gastric cancer, there was a significant increase in the level of ceruloplasmin compared with patients with gastric cancer in stages I-II of the disease (CP: p2–3 < 0.001)." (PMID 37509684, 2023). "In patients with gastric cancer at stages I–II of the disease, five strong correlations were found: Imax spon.—SOD, Imax spon.—GST, Imax spon.—GPO, Imax spon.—CP, Imax induced.—MDA." (PMID 37509684, 2023).
hereditary hemochromatosis (2 papers, 2010 to 2023). An inherited metabolic disorder characterized by iron accumulation in the tissues. "The observation that hepatic hepcidin mRNA expression in ACP patients and in dysmetabolic siderosis patients are comparable, but low in HFE hereditary hemochromatosis, suggests that CP but not HFE is dispensable for iron-mediated hepcidin regulation." (PMID 20801540, 2010).
Hyperinsulinemia (2 papers, 2023 to 2025). An increased concentration of insulin in the blood. "A FINS/CP ratio of over 9.3uIU/ng (0.19 molar ratio) was shown to be a good indicator for screening IAs positive in insulin or insulin analog-treated patients with hyperinsulinemia in clinical practice." (PMID 37324170, 2023). "The determination of FINS/CP ratios and subsequent PEG precipitation should also be performed to differentiate real hyperinsulinemia from IAs-related hyperinsulinemia, which has different clinical characteristics and pathogenesis." (PMID 37324170, 2023). "Patients with IAs usually have a higher FINS level, an unaffected C-peptide concentration and a higher FINS/CP ratio.We found that the FINS/CP ratio ≥ 9.3uIU/ng (0.19 molar ratio) demonstrated high sensitivity for screening the presence of IAs in patients with C-INS and hyperinsulinemia." (PMID 37324170, 2023).
hyperthyroidism (2 papers, 2018 to 2021). Overactivity of the thyroid gland resulting in overproduction of thyroid hormone and increased metabolic rate. "Plasma CP levels in patients with hyperthyroidism were also confirmed to be increased." (PMID 35222610, 2021).
IgA nephropathy (2 papers, 2019 to 2024). "Urinary exosomal aminopeptidase N, vasorin precursor, α-1-antitrypsin, and ceruloplasmin could differentiate IgA nephropathy from thin basement membrane nephropathy and healthy controls." (PMID 32082158, 2019). "For other glomerular diseases, a previous study using a proteomics approach has shown that urinary exosomal aminopeptidase N, vasorin precursor, α-1-antitrypsin, and ceruloplasmin could differentiate immunoglobulin A (IgA) nephropathy from thin basement membrane nephropathy and healthy controls." (PMID 32082158, 2019).
Impaired glucose tolerance (2 papers, 2022). An abnormal resistance to glucose, i.e., a reduction in the ability to maintain glucose levels in the blood stream within normal limits following oral or intravenous administration of glucose. "As a possible explanation, a previous study reported that the clearance of ceruloplasmin, IgG4, and IgG was significantly higher in the impaired glucose tolerance group and T2DM than in the control group." (PMID 35741222, 2022).
intracerebral hemorrhage (2 papers, 2017 to 2022). A cerebrovascular disorder characterized by bleeding into one or both cerebral hemispheres including the basal ganglia and the cerebral cortex. "Thus, a correlation between brain ceruloplasmin expression after experimental intracerebral hemorrhage and protection against iron-induced brain injury was revealed." (PMID 35806305, 2022). "5-FU, 5-fluorouracil; CP, complex partial; DIC, disseminated intravascular coagulation; GCSE, generalized convulsive status epilepticus; ICH, intracerebral hemorrhage; HSV, herpes simplex virus; NCSE, nonconvulsive status epilepticus; SAH, subarachnoid hemorrhage." (PMID 28979770, 2017).
iron disorders (2 papers, 2022 to 2024). "Copper accumulation can lead to not only cardiolipin fragmentation of the mitochondrial membrane causing mitochondrial dysfunction but ceruloplasmin reduction causing iron metabolism disorder." (PMID 36282481, 2022).
kidney (2 papers, 2020 to 2022). "CP-mediated kidney injury model was built up by using 20 mg/kg of CP." (PMID 33414838, 2020).
Klinefelter syndrome (2 papers, 2011 to 2022). A sex chromosome disorder caused by the presence of an extra X chromosome in the male karyotype. "Anagnostopoulos and co-workers reported that ceruloplasmin, alpha-1-antitrypsin, and zinc-alpha-2-glycoprotein are upregulated in specimens from pregnancies with Klinefelter syndrome fetuses, and were downregulated against proteins identified in specimens from normal fetuses." (PMID 36009368, 2022).
memory impairment (2 papers, 2019 to 2022). "Our results provide potential new strategies of CP supplementation for the treatment of learning and memory impairment in the young and suppression of CP to delay senescence in learning and memory in the old." (PMID 36443285, 2022). "CP expression was significantly downregulated in the hippocampus region of AD patients, resulting in memory impairment and increased iron accumulation." (PMID 31333395, 2019).
Nephropathy (2 papers, 2021 to 2022). A nonspecific term referring to disease or damage of the kidneys. "A damaged glomerulus due to nephropathy may cause greater dissociation of the copper/albumin and copper/ceruloplasmin complexes, and urinary copper overload may, in turn, play an important role in the progression of nephropathy." (PMID 36676942, 2022).
neuroblastoma (2 papers, 2016 to 2023). Neuroblastoma (NB) is the most common solid, extracranial childhood tumor. "Our study identified ATF5 as a metastasis promoter and CP-d/n-ATF5 as a potential antimetastatic therapeutic agent for neuroblastoma." (PMID 38014922, 2023). "Therapeutically, we showed that a cell-penetrating dominant-negative ATF5 peptide, CP-d/n-ATF5, inhibits neuroblastoma metastasis to the bone marrow and liver by inducing anoikis sensitivity in circulating tumor cells." (PMID 38014922, 2023). "In vitro, under adherent conditions, CP-d/n-ATF5 dose-dependently inhibited the growth of a panel of neuroblastoma cell lines, both MYCN-amplified and MYCN-non-amplified." (PMID 38014922, 2023). "The results of the CTG assay were very similar and showed that the two GA and CP-1 and CP-2 did not adversely affect the differentiated neuroblastoma cells, but treatment with CP-3 reduced the viability of the cells at both concentrations tested." (PMID 27764084, 2016). "In the case of neuroblastoma cells, we did not observe differentiation upon ATF5 depletion or CP-dn-ATF5 treatment, but rather the onset of apoptosis/anoikis." (PMID 38014922, 2023).
neuropathy (2 papers, 2014 to 2021). A disorder affecting the nervous system that manifests with pain, tingling, numbness, and/or muscle weakness. "The CP rs3816893 and rs1302552 SNPs, which were associated with DNP alone in this population, also showed strong associations with the presence of neuropathy symptoms in general, which included paresthesias and loss of sensation." (PMID 25144566, 2014).
Non-Alcoholic Steatohepatitis (2 papers, 2019 to 2022). "Increased production of ceruloplasmin could have been a response to significant weight loss or the presence of nonalcoholic steatohepatitis." (PMID 31275668, 2019).
nonalcoholic fatty liver disease (2 papers, 2019 to 2021). "The liver Cu deficiency plays a role in the pathogenesis of diseases such as nonalcoholic fatty liver disease, bile duct ligation-induced liver injury, fibrosis, inhibited ceruloplasmin activity, and disturbed heme oxygenase-1 gene expression." (PMID 30746586, 2019). "Interestingly, metabolic syndrome with NAFLD (nonalcoholic fatty liver disease) may lead to deranged hepatic synthesis of ceruloplasmin with altered blood levels of copper and iron." (PMID 34502369, 2021).
oesophageal cancer (2 papers, 2020 to 2023). "Serum levels of Cu, CP, ATP7A/7B, and the Cu:Zn ratio in serum are result-related markers and are resistant to treatment across the entire spectrum of gastrointestinal tumours including gastric and oesophageal cancers." (PMID 36839370, 2023).
pneumococcal infection (2 papers, 2019 to 2024). Infections with bacteria of the species streptococcus pneumoniae. "(a) Cp 090104 and CP-derived BLPs enhance the adaptive immune responses against pneumococcal infection." (PMID 38675794, 2024). "Bacterial counts declined in the lungs and a reduction in lung injury parameters on day 7 post-infection was observed in the mice treated with Cp 090104 or CP-derived BLPs before the pneumococcal infection." (PMID 38675794, 2024). "Recently, we evaluated the capacity of Cp 090104 and CP-derived BLPs, when co-administered with the pneumococcal vaccine Prevenar®13 via the nasal route, to improve the protection of mice against pneumococcal infection." (PMID 38675794, 2024). "The different types of specific immunoglobulins against S. pneumoniae, IgM, IgG, and IgA were enhanced in sera of the mice receiving the nasal pretreatment with Cp 090104 or CP-derived BLPs before pneumococcal infection in comparison to the control mice." (PMID 38675794, 2024). "The heightened levels of IFN-γ and IL-4 in BAL and serum samples from the mice treated with Cp 090104 or CP-derived BLPs during pneumococcal infection indicated an enhancement in the activation of Th1 and Th2 cellular immune defenses." (PMID 38675794, 2024). "Here, we assessed the effectiveness of nasal immunization with PSPF plus Cp 090104 and CP-derived BLPs in protecting against secondary pneumococcal infection using a well-established superinfection model with poly(I:C) and S. pneumoniae." (PMID 38675794, 2024). "We previously demonstrated the ability of the Cp 010904 strain and CP-derived BLPs to beneficially modulate the respiratory innate immunity against pneumococcal infection by evaluating immunological parameters at 2 days post-infection." (PMID 38675794, 2024). "These kinetic studies could help understanding better the immunological changes induced by Cp 090104 or CP-derived BLPs in the context of pneumococcal infection." (PMID 38675794, 2024).
primary immunodeficiency (2 papers, 2022 to 2023). "Furthermore, GSEA-GO and KEGG analyses of the CGGA dataset implied that CP was associated with the primary immunodeficiency and adaptive immune-associated pathways, such as T cell and B cell activation, antigen receptor-mediated signaling pathway, T cell receptor signaling pathways." (PMID 37637428, 2023).
renal carcinoma (2 papers, 2019 to 2021). A carcinoma arising from the epithelium of the renal parenchyma or the renal pelvis. "Tissue protein assays demonstrated that renal cancer highly expressed CP, while in vitro experiments showed that CP could promote the invasion of renal cancer cells." (PMID 34449964, 2021). "Tissue protein assays demonstrated that renal cancer highly expressed ceruloplasmin (CP), and in vitro experiments showed that CP could promote the invasion of renal cancer cells." (PMID 34449964, 2021). "They suggested 10 proteins for renal cancer exsome biomarker, 5 of which are abundant in renal cancer patients; matrix metalloproteinase 9 (MMP-9), ceruloplasmin (CP), podocalyxin (PODXL), dickkopf related protein 4 (DKK4) and carbonic anhydrase IX (CAIX)." (PMID 31686989, 2019).
scrapie (2 papers, 2012 to 2014). A fatal disease of the nervous system in sheep and goats, characterized by pruritus, debility, and locomotor incoordination. "Our findings suggest that CP deficiency may contribute to the neuronal degeneration observed in scrapie, although further analyses of brain expression and blood levels of CP will be required to determine its role in scrapie." (PMID 24450868, 2014). "Increased CP expression has been reported in leukocyte-depleted splenic cells from clinical scrapie-infected mice." (PMID 24450868, 2014). "However, we found that CP expression was significantly downregulated in the lymph nodes of scrapie-infected animals in the clinical stage of the disease." (PMID 24450868, 2014).
substance abuse (2 papers, 2020 to 2024). The use of a drug for a reason other than which it was intended or in a manner or in quantities other than directed. "In these cells, reinsertion of CP-AMPARs in adult animals can also be an important mechanism of plasticity underlying learning and substance abuse." (PMID 38380827, 2024).
syphilis (2 papers, 2016 to 2024). A contagious bacterial infection caused by the spirochete Treponema pallidum. "Her blood biochemistry test results were normal, including ceruloplasmin and ferritin levels and tests for syphilis." (PMID 27044537, 2016).
systemic sclerosis (2 papers, 2018 to 2025). A chronic disorder, possibly autoimmune, marked by excessive production of collagen which results in hardening and thickening of body tissues. "For instance, studies have shown that serum ceruloplasmin (CP) levels are significantly elevated in patients with systemic sclerosis-associated PAH and PAH mouse models." (PMID 40642746, 2025).
thin basement membrane nephropathy (2 papers, 2019 to 2020). "Higher levels of aminopeptidase N, vasorin precursor, α-1-antitrypsin, and ceruloplasmin have been used to distinguish between IgA and thin basement membrane nephropathy which is another common cause of glomerular hematuria." (PMID 32849923, 2020).